RNU6-1082P (RNA, U6 small nuclear 1082, pseudogene)
Gene: Small nuclear RNA gene on chromosome 9 (117,707,996 to 117,708,102, reverse strand). Ensembl gene ENSG00000201444.
Homologues: Orthologues: chimpanzee U6 (98% identical), macaque U6 (91% identical), mouse Gm26071 (87% identical), guinea pig U6 (82% identical). Paralogues in human: RNU6-33P (89% identical), RNU6-38P (89% identical), RNU6-480P (89% identical), RNU6-698P (89% identical), RNU6-86P (89% identical), RNU6-1 (88% identical), RNU6-2 (88% identical), RNU6-36P (88% identical), RNU6-39P (88% identical), RNU6-3P (88% identical), RNU6-40P (88% identical), RNU6-46P (88% identical), and 1285 more.